BHMT2 (betaine--homocysteine S-methyltransferase 2)
Description:
Involved in the regulation of homocysteine metabolism. Converts homocysteine to methionine using S-methylmethionine (SMM) as a methyl donor.
Tractability: Small molecule: an approved drug acts on it; it belongs to a druggable protein family. PROTAC: a small molecule that binds it is known.
Target class: Enzyme; Transferase
Gene: Protein-coding gene on chromosome 5 (79,069,636 to 79,090,069, forward strand). Ensembl gene ENSG00000132840.
Pathways (Reactome):
Metabolism: Sulfur amino acid metabolism
Gene Ontology:
Molecular function: betaine-homocysteine S-methyltransferase activity; S-methylmethionine-homocysteine S-methyltransferase activity; zinc ion binding; methyltransferase activity; S-methyltransferase activity
Biological process: amino-acid betaine metabolic process; L-methionine salvage; S-adenosylmethionine metabolic process; S-methylmethionine metabolic process; modified amino acid metabolic process
Cellular component: extracellular exosome; cytosol
Genetic constraint (gnomAD): Loss-of-function variants: 31 observed, 41.32 expected, observed/expected ratio (o/e) 0.75, 90% interval 0.56 to 1.01. The upper end of that interval is the gene's LOEUF score, 1.01, which puts it in group 4 of 6, group 1 being the genes least tolerant of losing a copy. Missense variants: 406 observed, 461.51 expected, observed/expected ratio (o/e) 0.88, 90% interval 0.81 to 0.95. Synonymous variants: 145 observed, 164.87 expected, observed/expected ratio (o/e) 0.88, 90% interval 0.77 to 1.01.
Homologues: Orthologues: dog BHMT2 (88% identical), guinea pig BHMT2 (87% identical), pig BHMT2 (86% identical), mouse Bhmt2 (86% identical), rat Bhmt2 (85% identical), tropical clawed frog bhmt (73% identical), zebrafish bhmt (70% identical). Paralogues in human: BHMT (78% identical), MTR (27% identical), MTHFR (23% identical), UROD (14% identical).
Diseases named in the same sentence as BHMT2 in open-access papers:
BHMT2 is named in the same sentence as 18 diseases in open-access papers, as found by Europe PMC text mining. Sharing a sentence is not in itself a finding about the gene and the disease. The quoted sentences say what the papers report.
Obesity (2 papers, 2021 to 2025). Accumulation of substantial excess body fat. "BHMT2 is involved in adolescent obesity by affecting the metabolism of amino acids, that may be candidate genes in the etiology of obesity." (PMID 34869329, 2021).
bladder cancer (1 paper, 2022). "We identified three genes, PTHLH, BHMT2, and NGFR, involved in bladder cancer immunotherapy." (PMID 36439109, 2022). "Our results indicated that PTHLH, BHMT2, and NGFR might be novel targets for bladder cancer immunotherapy and prognosis." (PMID 36439109, 2022). "For the mRNA level, BHMT2 was lower in bladder cancer tissue, but not in protein levels." (PMID 36439109, 2022).
cleft palate (1 paper, 2014). Cleft palate is a fissure type embryopathy that affects the soft and hard palate to varying degrees. "Interestingly, variations in BHMT1 and BHMT2 have also been implicated in the development of cleft palate in certain human populations." (PMID 25165462, 2014).
liver diseases (1 paper, 2025). "Dysregulation of BHMT2 and MAT1A has been implicated in various pathological conditions, such as liver diseases and cancer." (PMID 41219226, 2025).
necrotizing enterocolitis (1 paper, 2025). Necrotizing enterocolitis (NEC) is a devastating disease that affects mostly the intestine of premature infants. "The findings of this study unravel a previously unrecognized regulatory axis involving AHSG, BHMT2, and MAT1A that orchestrates macrophage polarization and contributes to the exacerbation of necrotizing enterocolitis." (PMID 41219226, 2025).
viral infection (1 paper, 2014). "Also included in the F344-virus group were Dmgdh and Bhmt2, genes involved in the choline metabolism pathway, a source of key lipids involved in lung surfactant production and host defense against viral infection." (PMID 25437859, 2014).
cancer (3 papers, 2015 to 2024). A tumor composed of atypical neoplastic, often pleomorphic cells that invade other tissues. "Results indicated high expression of IL4I1, TDO2, NIT2, and IDO1, while IDO2, ADI1, DDC, HPD, BHMT2 exhibited low expression in most cancers." (PMID 38691253, 2024). "Other genes involved in one-carbon metabolism were found transcriptionally repressed in HCC tissue, although the methylation pattern was unchanged in BHMT1, BHMT2, CBS, GNMT, and MTHFD2L in cancer as compared to cancer-free tissue or decreased in FOLH1." (PMID 25945129, 2015).
BHMT2 also shares sentences with these, for which no sentence is quoted: amyotrophic lateral sclerosis (1 paper); atherosclerosis (1); breast carcinoma (1); cleft lip (1); fatty liver disease (1); hepatocellular carcinoma (1); hypospadias (1); neurodegenerative disease (1); ovarian carcinoma (1); Parkinson disease (1); tumor (1).